BRCA1 (BRCA1 DNA repair associated)
Diseases named in the same sentence as BRCA1 in open-access papers (continued):
Sharing a sentence is not in itself a finding about the gene and the disease.
pancreatic adenocarcinoma (22 papers, 2014 to 2025). "In a report of resected pancreatic adenocarcinoma, patients with germline BRCA1/BRCA2 and PALB2 mutations had better overall survival (OS) than patients without such mutations (median OS 46.6 months versus 23.2 months)." (PMID 36975505, 2023). "A phase II study of olaparib monotherapy in patients with various metastatic malignancies and germline BRCA1/BRCA2 mutations included 23 patients with pancreatic adenocarcinoma." (PMID 36975505, 2023). "A complete response was observed following low-dose palliative radiation and chemotherapy in a 54-year-old female patient who was BRCA1-positive and presented with stage IV pancreatic adenocarcinoma." (PMID 41466916, 2025). "In unselected cases of pancreatic adenocarcinoma, pathogenic mutations in BRCA2 are identified in up to 2%, while mutations in BRCA1 are observed in 1% or less." (PMID 38809921, 2024). "Rucaparib was tested in a phase II trial in 16 germline BRCA1 (n= 12)/BRCA2 (n = 4) mutant pancreatic adenocarcinoma patients and 3 additional patients with somatic BRCA2 mutations who had received one or two chemotherapy lines." (PMID 36975505, 2023). "The National Comprehensive Cancer Network (NCCN) recommends BRCA1/2 analysis for all diagnosed with pancreatic adenocarcinoma." (PMID 32793315, 2020). "RUCAPANC, an open-label phase 2 trial investigated rucaparib, an oral PARP inhibitor, in previously treated patients with BRCA1/2 mutant pancreatic adenocarcinoma." (PMID 29891787, 2018). "The optimal chemotherapy regimen to use for BRCA1 or 2 mutation carriers with pancreatic adenocarcinoma is not established." (PMID 29777302, 2018). "In the pancreatic adenocarcinoma cases of the project GENIE, which included 5262 cases profiled, the most prevalent oncogenic or likely oncogenic mutations in DDR-related genes were in ATM and in BRCA2, followed by lower frequencies in BRCA1, PALB2, ATR and BRIP1 and a few cases in other genes." (PMID 36975505, 2023).
pancreatic ductal adenocarcinoma (22 papers, 2012 to 2025). An infiltrating adenocarcinoma that arises from the epithelial cells of the pancreas. "BRCA1/2 mutations can increase the possibility of pancreatic ductal adenocarcinoma (PDAC), however, their impact on the clinical features of the disease is less clear." (PMID 38577595, 2024). "Olaparib has been approved as a therapeutic option for metastatic pancreatic ductal adenocarcinoma patients with BRCA1/2 mutations." (PMID 39187531, 2024). "Studies conducted using comprehensive genomic profiling (CGP) tests have revealed that approximately 20% of patients with pancreatic ductal adenocarcinoma show mutations in homologous recombination genes, including BRCA1/2 and PALB234,35." (PMID 39304727, 2024). "For the small subset of pancreatic ductal adenocarcinoma (PDAC) patients with loss-of-function mutations to BRCA1/2 or PALB2, both first-line and maintenance therapy differs significantly." (PMID 35205643, 2022). "For this purpose, we used conditional null alleles of Palb2 (Palb2flox2-3), Brca1 (Brca1flox2) and Brca2 (Brca2flox3-4) in combination with the well characterized Pdx1-Cre transgene that has been extensively used for modeling pancreatic ductal adenocarcinoma (PDAC) in mice." (PMID 31877165, 2019). "For example, a study involving 854 patients with pancreatic ductal adenocarcinoma showed that 12 patients (1.4 %) had BRCA2 and 3 patients (0.35 %) had BRCA1 deleterious germline mutations." (PMID 33563323, 2021). "Approximately 4% of all patients with pancreatic ductal adenocarcinoma have an underlying gene defect, with ATM, BRCA1/2, and PALB2 being the most commonly affected genes." (PMID 30736435, 2019). "BRCA1 and BRCA2 play pivotal roles in DNA homologous recombination repair (HRR), and germline BRCA1/2 mutations reportedly increase risk of pancreatic ductal adenocarcinoma (PDAC)." (PMID 29731985, 2018). "Recently, inherited mutations in correlation with PDAC have gained focused attention, and a pathogenic BRCA1 and BRCA2 mutation was identified in a large cohort in 4.6% among pancreatic ductal adenocarcinoma patients." (PMID 28978057, 2017). "Multiple genes that are associated with well-known hereditary cancer syndromes such as BRCA1 and BRCA2, PALB2, CDKN2A, ATM and the DNA mismatch repair genes were found to be associated with pancreatic ductal adenocarcinoma as well." (PMID 28978057, 2017). "Using NetRank, we identified seven genes (STAT3, FOS, JUN, SP1, CDX2, CEBPA, and BRCA1) as most relevant for predicting survival in patients with pancreatic ductal adenocarcinoma." (PMID 22615549, 2012). "Hence, sequencing of gHRR genes other than BRCA1/2 should be routinely offered as part of the biological characterization of pancreatic ductal adenocarcinoma." (PMID 33800556, 2021). "An IF and IHC panel for BRCA1 and BRCA2 expression was performed on normal pancreas, pancreatic ductal adenocarcinoma (PDAC), and the PACC PDTX model." (PMID 27165126, 2016).
squamous cell carcinoma (22 papers, 2007 to 2025). A carcinoma arising from squamous epithelial cells. "Both penile tumors (squamous cell carcinoma) exhibited mutations in BRCA1 and FAS, as well as ARID1A, CHEK2, BRCA2, and were Human Papillomavirus (HPV) positive." (PMID 41395625, 2025). "For example, cisplatin-sensitivity-associated lncRNA (CISAL) inhibits BRCA1 transcription and thereby controls cisplatin sensitivity in squamous cell carcinoma." (PMID 34497804, 2021). "Mutations of all; PALB2, BRCA1, BRCA2 and CHEK2 were most frequent in cutaneous squamous cell carcinomas covering ~60% of mutations in each of the genes." (PMID 34084283, 2021). "We investigated the relationship between peripheral blood RRM1, ERCC1, and BRCA1 expression levels with histopathology classifications (squamous cell carcinoma, adenocarcinoma), smoking, age, clinical staging (IIIB and IV), and chemotherapy response." (PMID 24591771, 2014). "In this multi-center study, the author’s intention was to investigate the predictive and prognostic role of BRCA1 level in squamous cell carcinoma (SCC) and adenocarcinoma (ADC), so both OS and EFS were conducted in 2 groups (SCC and ADC)." (PMID 23497550, 2013). "For the BRCA1, as the expression values were significantly higher in squamous cell carcinomas in comparison with the adenocarcinomas (P=0.001), the cutoff values were calculated according to median expression levels in each group of squamous and non-squamous histology." (PMID 21157449, 2011). "In with squamous cell carcinoma, those ever smoked, those with ECOG performance status of 1, or those at stage III, BRCA1 rs1799966 TC+CC genotypes predicted a longer OS than the TT genotype (log-rank p<0.05 for all)." (PMID 24933103, 2014). "We observed a different expression pattern according to histology, with higher levels of BRCA1, 53BP1 and UBC9 expression in squamous cell carcinomas." (PMID 24197907, 2013). "In contrast, BRCA1 expression did not correlate with survival outcomes in squamous cell carcinoma patients." (PMID 38090061, 2023). "Chu and colleagues described the mutational characterization from whole exome sequencing of a case of PSCCT, including TMPRSS2, BRCA1, ASPSCR1, and others, but the identified driver mutations common in squamous carcinomas are absent." (PMID 36329478, 2022). "Higher proportion of squamous cell carcinoma (SCC, 93.2%) was observed in the BRCA1 positive group than in the BRCA1 negative group (69.2%)." (PMID 34820332, 2021).
anemia (21 papers, 2008 to 2026). A reduction in the number of red blood cells, the amount of hemoglobin, and/or the volume of packed red blood cells. "This implies that when BRCA1/2 mutations occur, bone marrow failure, resulting in anemia, is likely to occur." (PMID 36267984, 2022). "Patients with BRCA1/2 mutations are at risk of FA, which may have affected the frequency and severity of olaparib-induced anemia." (PMID 36267984, 2022). "These SE events contained several DNA repair genes regulated by SmD2, such as BRCA1 and Fanconi anemia subtype (FANC) genes, which we validated through RT-PCR." (PMID 38890388, 2024). "The Fanconi anaemia proteins together with BRCA1/FANCS and BRCA2/FANCD1 act in a common pathway, FANCA/BRCA pathway, to coordinate the cellular response to DNA damage, driving DNA repair through homologous recombination (HR)." (PMID 36622663, 2023). "Among men with grade 3-4 anemia, 56.4% (22/39) had BRCA1/2 alterations and 72.7% (16/22) of these men had a duration of treatment 6 months or longer versus 56.4% (22/39) of men in the overall population with grade 3-4 anemia." (PMID 36124924, 2022). "Indeed, BRCA1 and FANCA (a member of the Fanconi Anemia family of proteins) are involved in detecting DNA damage, causing cell cycle arrest and allowing DNA repair, which contributes to chemoresistance, while disruption of the BRCA1 pathway may promote sensitivity to platinum-based therapies." (PMID 18302766, 2008). "Additionally, BRCA1/2 mutation was suggested to be a patient-related risk factor for anemia regardless of severity." (PMID 36267984, 2022). "Moreover, the present study is also the first to identify BRCA1/2 mutation as a possible patient-related risk factor for anemia regardless of severity." (PMID 36267984, 2022). "In addition, BRCA1/2 mutation was suggested to be a patient-related risk factor for anemia regardless of severity." (PMID 36267984, 2022). "Several BRCA1/2 interactors, such as PALB2 (FANCN), RAD51 (FANCR), and BRIP1 (FANCJ), are also Fanconi anemia proteins." (PMID 40841483, 2026). "CDK12 is involved in the DNA-damage repair (DDR) pathway by regulating the expression of several DDR machinery components, including BRCA1, ATM, ATR, and Fanconi anemia (FANC) genes." (PMID 40148269, 2025). "Mammalian RAD51, in collaboration with BRCA1, BRCA2, and Fanconi anemia proteins, plays a critical role in preventing nascent DNA degradation by MRE11." (PMID 40737093, 2025). "For the 33 patients in the olaparib arm identified with a somatic BRCA1 or BRCA2 alteration, 18% had grade ≥3 anaemia." (PMID 35598359, 2022). "Therefore, the effect of BRCA1/2 mutations on anemia is not significant." (PMID 36267984, 2022). "BRIP1, located at 17q22, is a Fanconi anaemia gene (FANCJ) that directly interacts with the BRCT domain of BRCA1 and has a role in DNA damage repair." (PMID 19935797, 2009). "Additionally, among 42 patients in the olaparib arm identified with either a germline BRCA1 or BRCA2 alteration, 26% of these patients had grade ≥3 anaemia." (PMID 35598359, 2022). "BRCA1 and 2 interacts with a number of other DNA repair proteins to form a complex system for DNA damage repair, including ATM, RAD51, PALB2, MRE11A, RAD50, NBN, and the Fanconi anemia proteins." (PMID 35785170, 2022).
depression (20 papers, 2000 to 2025). "The eventual relation between clinical presentation, PRL levels, depression, and BRCA1 mutation will be discussed." (PMID 30518416, 2018). "We describe a very rare giant prolactinoma in a young woman with breast cancer gene 1 (BRCA1) mutation and with depressive syndrome, who required an urgent surgical procedure for an unusual life-threatening acute hydrocephalus." (PMID 30518416, 2018). "Of these depression measures, the CES-D appeared to be the most sensitive in detecting depression in BRCA1/2 carriers." (PMID 37185387, 2023). "The intent of this study was to evaluate the effect that an awareness of being a BRCA1 or BRCA2 mutation carrier has on the attitude towards prophylactic surgery and on developing depression symptoms." (PMID 10755396, 2000).
stomach cancer (19 papers, 2015 to 2025). "Therefore, we sought to evaluate the prevalence of BRCA1/2 mutations in each molecular gastric tumor subtype." (PMID 32070411, 2020).
esophageal cancer (18 papers, 2013 to 2025). A primary or metastatic malignant neoplasm involving the esophagus. "In this study, we firstly determined whether the levels of BRCA1 mRNA expression as predictive and prognostic biomarker were associated with clinical outcomes in esophageal cancer patients who received cisplatin- or docetaxel-based treatments." (PMID 23326344, 2013). "The father of the patient with BRCA2 c.6468_6469delTC/BIC: 6696delTC had laryngeal cancer, and the brother and father of the carrier of PV BRCA1 c.2498delT had gastric and esophageal cancer." (PMID 37791908, 2023). "The results of this large-scale registry-based study suggest that pathogenic variants in BRCA1 and/or BRCA2 are associated with increased risk of biliary tract, gastric, and esophageal cancers." (PMID 35420638, 2022). "BRCA1 was discovered to be involved in the inverse resistance relationship between cisplatin- and docetaxel-based treatments in esophageal cancer patients." (PMID 23326344, 2013). "Nevertheless, we didn't observe the effect of BRCA1 on resistance of radiotherapy for patients with esophageal cancer." (PMID 23326344, 2013). "In the whole cohort, 144 esophageal cancer patients had a mOS of 13.0 months (95% CI: 11.5–14.5 months), without statistical significance between the high and low expression of BRCA1 (13.0 vs 12.8, P = 0.817)." (PMID 23326344, 2013). "In addition, the family with lung and esophageal cancers, two VUS BRCA2 and MRE11A mutations were detected in two BC patients with BRCA1 likely pathogenic mutation." (PMID 30982232, 2019). "LOH and MSI frequencies were evaluated at chromosomal regions known to be frequently altered in sporadic esophageal cancer with particular attention to loci nearby genes involved in DNA double strand break (DSB) or in the oxidative damage repair pathways (i.e. BRCA1, BRCA2, RAD1 and MSRA)." (PMID 25611972, 2015). "BRCA1 mRNA expression could be used as a predictive and prognostic marker in esophageal cancer who underwent first-line cisplatin- or docetaxel-based treatments." (PMID 23326344, 2013). "It remains unclear how variations in BRCA1 expression influence clinical outcomes in esophageal cancer." (PMID 23326344, 2013). "In present study, we firstly applied qPCR analysis of BRCA1 mRNA expression in formalin-fixed paraffin-embedded tumor tissue in advanced and metastasis esophageal cancer and evaluated the relationship between BRCA1 mRNA expression levels and cisplatin- or docetaxel-based treatments." (PMID 23326344, 2013). "However, there was no definite link between the occurrence of esophageal cancer and the BRCA1 Asp1362fs mutation." (PMID 34570441, 2021). "However, we provide the first evidence to support the tumor mRNA expression levels of BRCA1 as predictive and prognostic marker in esophageal cancer with cisplatin- or docetaxel-based treatments and indicated the need to further validate in a large number of patients prospectively." (PMID 23326344, 2013). "However, no studies have addressed how variations in BRCA1 expressions influence clinical outcomes in patients with esophageal cancer treated with these chemotherapeutic agents." (PMID 23326344, 2013). "Notably, out of four esophageal cancer samples, three samples had a GIS ≥42, although harboring no alterations in the genes BRCA1/2." (PMID 40278800, 2025).
Familial adenomatous polyposis (18 papers, 2006 to 2025). Familial adenomatous polyposis (FAP) is characterized by the development of hundreds to thousands of adenomas in the rectum and colon during the second decade of life. "For instance, one can easily envision the increase in quality of life in patients with familial adenomatous polyposis or somatic BRCA1 and 2 mutations where localized treatment leads to increased p16Ink4a activity, as seen in the naked mole rat, and thus prevents tumour formation." (PMID 34093847, 2021). "As expected, MUTYH associated with recessive familial adenomatous polyposis, the only two homozygotes of which also carry biallelic MUTYH variants, had the highest allele frequency, followed by VHL, BRCA1, BRCA2, and PALB2." (PMID 39301547, 2024).